CD4 (CD4 molecule)
Diseases named in the same sentence as CD4 in open-access papers (continued):
Sharing a sentence is not in itself a finding about the gene and the disease.
cancer (continued). "Importantly, in the context of cancer immunotherapy, IL-2/CD25 FP was found to amplify vaccine-induced, neoantigen-specific CD4+ and CD8+ T cell responses, thereby enhancing antitumor immunity." (PMID 40789741, 2025). "A meta-analysis involving 877 cancer patients indicated a significant reduction in the number of CD3+ T lymphocytes and CD4+ T lymphocytes in peripheral blood following conventional radiotherapy, whereas the count of CD8+ T lymphocytes remained largely unchanged." (PMID 40740877, 2025). "Consistent with our previous findings, STS patients showed a significant increase in circulating CD8+ T cells and a slight decrease in CD4+ T cells compared with healthy donors, in line with reports of elevated antigen-specific CD8+ T cells in cancer patients, which is more evident in P3 patients." (PMID 41221282, 2025). "The chimeric protein SA-4–1BBL alone also protected mice against tumor challenge in various preclinical mouse models via non-specific activation of CD4+ T and natural killer cells demonstrating its ability to prime the immune system for cancer prevention." (PMID 40437549, 2025). "Changes in the CD4+/CD8+ ratio are significant in immune surveillance across various cancers, yet their specific role in DLBCL has not been fully explored." (PMID 41244913, 2025). "In these cancers, the ALBI’s albumin component reflects nutritional status, while elevated bilirubin may impair antitumor immunity by suppressing CD4+ T-cell function." (PMID 40722777, 2025). "Specifically, across various cancer types, HuR expression exhibited a negative correlation with the distribution of antitumor immune cells, including activated CD4 + T cells, activated CD8 + T cells, and activated dendritic cells, among others." (PMID 40853971, 2025). "Given the critical role of immune homeostasis in cancer development and autoimmune diseases, our study focuses on the effects of ATR on the differentiation in T-helper (Th) subsets of peripheral human CD4+ T cells in primary culture through the study of phenotypical markers and cytokine expression." (PMID 40025135, 2025). "Cancers with many ICs in that study were also enriched in the CD8 and CD4 cells." (PMID 41000797, 2025). "Therapeutic cancer vaccines are designed to stimulate the immune system to recognize and eliminate cancer cells by activating immune cells such as CD8+ cytotoxic T cells and CD4+ helper T cells." (PMID 41516128, 2025). "To determine whether CCR9 is involved in the recruitment of CD4+ and CD8+ effector T cells during CRC development, we analyzed the cLP infiltrate under basal (CTRL), inflammatory (DSS) and cancer promoting conditions (AOM/DSS), using flow cytometry." (PMID 40305493, 2025). "The occurrence and severity of other HIV/AIDS-defining cancers (i.e., Kaposi Sarcoma and non-Hodgins lymphoma) have declined dramatically following CD4 T-cell rebound upon adherence to ART." (PMID 40661570, 2025). "Further analysis suggests that these worse survival outcomes may be due to increased aggressive cancer pathways, including epithelial–mesenchymal transition and hypoxia, along with decreased CD8+ and CD4+ T cell infiltration in high-PIEZO1 HR-negative tumors." (PMID 38398074, 2024). "Moreover, high B cell, CD4+ T cell, CD8+ T cell, and dendritic cell infiltration improved cancer patients’ survival rate at 10 years." (PMID 39432636, 2024). "Furthermore, the TME contains macrophages, CD4+ T cells, B cells, CD8+ T cells, and neutrophils, which are involved in the development of cancer." (PMID 38164277, 2024). "Both HLA-A*03:01 and HLA-A*11:01–restricted TCR-redirected CD8+ T cells exhibited potent lytic activity against KRASG12V cancers, while only HLA-A*11:01–restricted TCR-T CD4+ T cells exhibited antitumor effector functions consistent with partial coreceptor dependence." (PMID 39287991, 2024). "As we here focus the role of CD8+ T cells in cancer immunotherapy, the anti-cancer efficacies of CD4+ T cells are by no means excluded." (PMID 38685033, 2024).
cancer (continued). "Generally, we observed higher SIV CD8 T-cell response than CD4 T-cell in our study, which further illustrates the potential of arenavirus vectors in generating strong CD8 T-cell immunity in cancer models in mice and in clinical-trial settings." (PMID 39066373, 2024). "Notably, based on the results of this experiment, it is presumed that DCs that have taken up cancer antigens activate CD8+ and CD4+ T cells in the spleen, and that CTL cells and Treg cells accumulate in the spleen." (PMID 39150932, 2024). "CD4+ T cells play a crucial role in the immune response against cancer by activating and directing other immune cells, such as CD8+ T cells, NK cells, and macrophages, to attack cancer cells." (PMID 38650948, 2024). "In turn, Foxp3-expressing CD4+ and CD8+ Treg cells are known to inhibit the anti-cancer immunity." (PMID 39845953, 2024). "The pan-cancer immune cell infiltration determined using the TIMER method showed that among 31 cancers, LINC01614 expression was correlated with six major immune cells: B cells, CD4+ T cells, CD8+ T cells, neutrophils, macrophages, and dendritic cells." (PMID 38655053, 2024). "CD8+ T cell effector differentiation and activation required CD4+ T cells, meanwhile, CD4+ T cells during the effector phase could license CD8+ T cell cytotoxicity and CD8+ T cell-mediated cancer cell elimination." (PMID 39582060, 2024). "Whether CD4:CD8 ratio or CD8 cell counts may represent markers for innate and adaptive immune activation that are predictive for specific type of cancers requires additional evidence." (PMID 38092042, 2024). "Considering CD4+ T cell could help CD8+ T cell‐mediate cytotoxicity and directly kill the cancer cells, future research are warranted to clarify the role of CD4+ T cell in sex‐based heterogeneity of treatment response." (PMID 38899854, 2024). "Forkhead box P (FOXP) TFs—FOXP1, FOXP2, FOXP3, and FOXP4—are involved in embryonic development, immune disorders, and cancer progression, but FOXP3’s targeting of CD4 + CD25+ regulatory T (Treg) cells and its dual role as an OCG or tumor suppressor in cancers are unclear and controversial." (PMID 38827026, 2024). "There is evidence suggesting that BRAF and MEK inhibition induces CD4 and CD8 T lymphocytes, boosting their cytotoxicity against cancer cells, which is evident by elevated granzyme B and perforin levels, and an elevated expression of cytotoxic T-lymphocyte-associated protein-4 (CTLA-4)." (PMID 38731852, 2024). "The relationship between cancer and lower CD4 cell counts in CVID is not clearly established, as we have found in our cohort." (PMID 39478863, 2024). "Therefore, we conclude that CD4+T cells play an important role in HCC immune surveillance, and cancer cell-derived Bcl6 inhibited CD4+T cell function to assist HCC immune evasion." (PMID 38956432, 2024). "TIMER algorithm results showed that NXPH4 exhibited a negative link to CD8+ T-cells, CD4+ T-cells, neutrophils, macrophages, and B-cells in most cancers." (PMID 38613793, 2024). "However, the levels of CD4+CD25+FOXP3+ and follicular Tregs were significantly increased in both the peripheral blood and breast tissues of patients with BC in all cancer subtypes." (PMID 38303018, 2024). "Peptide-based cancer vaccines require epitopes for both CD8+ and CD4+ T cells." (PMID 38519525, 2024). "As a result, this system provided robust CD4+ and CD8+ immunity for cancer vaccines." (PMID 38528828, 2024). "Low CD4+ cell counts impair the immune system’s ability to clear HR-HPV infections, due to the lack of effective signaling for a robust cytotoxic response and increase the incidence of HPV-related cancers." (PMID 39902182, 2024). "Despite the limitations of this study, TLR expression on different lymphocyte subpopulations (such as CD4+, CD8+, and CD19+) may influence the way the immune system recognizes and responds to cancer cells." (PMID 38792335, 2024).
cancer (continued). "Poly(lactic-co-glycolic acid) (PLGA) nanoparticles functionalized with cancer cell membrane not only enhanced cancer cell-CAF interactions, but also increased antigen uptake, stimulating CD8+ and CD4+ T cells through MHC-I and MHC-II, thus promoting cancer immunotherapy." (PMID 38566199, 2024). "This suggests the potential to develop CD4+ T cells as immunotherapy targets in the future, especially for the patients with cancer who have failed to respond to CD8+ T cell therapy." (PMID 38482008, 2024). "CD4+ and CD8+ TSTR cells have been shown to be clinically relevant in cancer treatment." (PMID 38848147, 2024). "CD4+ and CD8+ cells play important roles in cancer immunomodulatory and immunosurveillance." (PMID 38368407, 2024). "Notably, higher levels of PSME3 exhibited a robust positive correlation with neutrophils, B cells, CD4 T cells, CD8 T cells, and M2 macrophages in cancers such as HNSC, KIRC, KICH, PRAD, and UVM." (PMID 38312840, 2024). "When employed as cancer vaccines, numerous peptides with high presentation scores failed to elicit CD4+ responses." (PMID 39582860, 2024). "LAG3 is expressed in CD4 and CD8+ T cells, as well as T regs, and is required for optimal T cell regulation and homeostasis, and FGL1 was found to be highly expressed in human cancer cells." (PMID 39120585, 2024). "CD4+T cells and CD8+ T cells play pivotal roles in the anti-cancer immune response." (PMID 38348038, 2024). "Our study demonstrates a positive association between NRAV and various immune cell types, including B cells, CD4+ T cells, CD8+ T cells, neutrophils, macrophages, and DC cells, in multiple cancer types such as KIRC, LGG, PRAD, LIHC, USC, GBMLGG, KICH, and DLBC." (PMID 38560576, 2024). "Our findings show that cancer treatment in patients with solid tumors does not compromise the quality of mRNA-1273-induced CD4 and CD8 T cell responses, aligning closely with responses observed in the general population." (PMID 39257577, 2024). "Next, whether the antitumor efficacy of the in situ cancer vaccine was mediated by immune effector cells in the 4T1 mouse model via depleting CD8+ and/or CD4+ T cells was evaluated." (PMID 38678042, 2024). "We analyzed the relationships between VDR expression and immune infiltration levels of NK cells, CD4+ T cells, CD8+ T cells, Tregs, B cells, cancer-related fibroblasts, macrophages, neutrophils, myeloid dendritic cells, and monocytes in various cancer types in TCGA database." (PMID 38639057, 2024). "Personalized vaccines can induce and activate CD4 + T helper 1 cells and CD8 + T cells to target neoantigens and kill cancer cells, resulting in the release of cancer antigens and positively promoting the “cancer-immunity cycle”." (PMID 38898505, 2024). "Both CD4+ and CD8+ T cells are critical in protecting the host against pathogens, with CD8+ T cells being particularly important in fighting intracellular pathogens including viruses and bacteria, as well as in eliminating malignant cells in cancer." (PMID 39250522, 2024). "Another subtype, Th17 CD4+, releases TGF-β, which is known to encourage cancer cell progression." (PMID 39050852, 2024). "In addition, KLK8 expression is negatively correlated with cancer-killing effector cells, such as CD8 + T cells which repress cancer progression by the direct killing effects, and CD4+ Th1 cells which enhance the cytotoxic activity of CD8 + T cells." (PMID 38273291, 2024). "Macrophages engulf damaged cells and present cancer antigens to CD4+ lymphocytes, which in turn stimulate cytotoxic CD8+ lymphocytes capable of directly destroying cells—in this way, the immune system is able to recognize the cancer cell and destroy it." (PMID 39065781, 2024). "When all patients were classified as 200–400 cells/mm3, 400–800 cells/mm3 and 800–1500 cells/mm3 according to CD4+ cell count regardless of cancer type, the prevalence rates were 16,6% (1/6), 30,5% (22/72) and 6,25% (1/16), respectively." (PMID 38926815, 2024).
cancer (continued). "Comparing HER2 positive and HER2 negative cancers we identified that HER2 positivity is associated with enrichment of CD4 T cells and less proliferating CD4 Th cells and proliferating CD8 T cells compared to HER2 negative tumors." (PMID 38638445, 2024). "In parallel, naïve CD4 and CD8 T cells were co-cultured with the cancer cells directly." (PMID 39516494, 2024). "However, recent studies show that CD4+ T cells can promote and maintain CD8+ T cell response through cytokines production or having a cytotoxic role in cancer with the secretion of perforins, granzyme as well as PD-1, TRAIL and FasL." (PMID 38816839, 2024). "TIM3 showed co-expression with PD1 in both CD4+ and CD8+ T cells of preclinical cancer models." (PMID 38338672, 2024). "This shows that our finding of increased CD4+PD1+ subpopulations in INR is independent of the higher incidence of history of cancers observed in INR." (PMID 38779686, 2024). "For different CD4+ T cell types, LINC01614 showed significant correlations in 20 cancer types." (PMID 38655053, 2024). "In CAR-T cell therapy, T cells (including both CD4 and CD8 T cells) from cancer patients are transduced ex vivo with retroviral/lentiviral vectors expressing an antibody-based receptor specific for an antigen expressed on the cancer cells." (PMID 38789421, 2024). "The significantly increased presence of CD4+ Tregs, especially those that are PD-1+, in FLC could contribute to the decreased clonality and spatial separation of effector T cells from the carcinoma cells." (PMID 38429349, 2024). "MAGEA4 is an interesting candidate for targeted immunotherapy, and recently a MAGEA4‐reactive, HLA‐A2‐restricted T‐cell receptor was engineered, showing effectivity and safety in either CD4 or CD8 preclinical assays, suggesting a clinical strategy for an agnostic treatment of MAGE4 positive cancer." (PMID 37341056, 2023). "Overall, The percentage of PD-1+CD45+ cells (R2 = 0.01, P = 0.0001), PD-1+CD3+ T cells (R2 = 0.015, P < 0.0001), PD-1+CD4+ Th cells (R2 = 0.02, P < 0.0001) and PD-1+CD3+CD8+ CTL (R2 = 0.006, P = 0.0036) showed an increase trend with age in both cancer patients and healthy individuals." (PMID 38102684, 2023). "These cells can induce CD4+ T-cell responses and IL-17 production, but they have not been in cancer-free lymph nodes, indicating the need for a cancer niche for their function." (PMID 36949244, 2023). "Except for the BLCA, in the other five kinds of cancer, low expression of COPZ1 exhibited more antitumor immune cells infiltration, including B cells, neutrophils, CD8+T cells, CD4+T cells and M1 macrophages, while high expression of COPZ1 associated with more Tregs infiltration." (PMID 37107648, 2023). "In most cancers, the expression of SLC1A5 is positively correlated with the infiltration of macrophages, CD4+ T cells, CD8+ T cells, dendritic cells, monocytes, MDSCs, and CAFs and negatively correlated with the infiltration of monocyte, HSC and Endo progenitors." (PMID 37566748, 2023). "Cancer vaccines, an important element of cancer immunotherapy, function by presenting an exogenous source of TAA proteins, peptides, and antigenic epitopes to CD4+ T cells via major histocompatibility complex class II (MHC-II) and to CD8+ T cells via major histocompatibility complex class I (MHC-I)." (PMID 37731507, 2023). "In addition to CD4+ Tfh and CD8+ Tex subsets, CXCL13+ T cells also had a high proportion in Th17 and CD8+ Tem subsets in cancer tissues." (PMID 37675100, 2023). "This corrective action of cancer on SARS-CoV-2-related inflammation does not seem to be unidirectional as COV/CA patients display enhanced activation of HLA-DR+CD38+CD4+ T cells, and increased IFNγ expression in PBMCs." (PMID 37063865, 2023). "Moreover, our study showed the percentage of PD-1+CD45+ cells, PD-1+CD3+ T cells, PD-1+CD3+CD4+ Th cells, PD-1+CD3+CD8+ CTL varied among major cancer types." (PMID 38102684, 2023).
cancer (continued). "We found that multiple RESs in CAVIN1 3’UTR were correlated with resting CD4+ memory T cells in at least six cancer types, seven in IGAX 3’UTR with M2 macrophages in at least six cancer types, and one in VWA8 intron with M1 macrophages in six cancer types." (PMID 36969056, 2023). "Both CD163 and CD4 + CXCR5 can be regarded as prognostic predictors for CRC patients to facilitate the evaluation of cancer prognosis and TME status, thereby optimizing individualized treatment plans and improving cancer patient survival." (PMID 36859111, 2023). "However, most vaccine therapies for cancer have focused on cytotoxic T lymphocyte CD8+ (CTL) activation, ignoring the CD4+ helper T cells that play an important role in full CTL activation." (PMID 36980665, 2023). "The result demonstrated that SERPINA1 expression presented strong connections to B cells in 25 cancer types, CD4+ T cells in 28 cancer types, CD8+ T cells in 25 cancer types, neutrophils in 32 cancer types, macrophages in 31 cancer types, and dendritic cells (DCs) in 32 cancer types." (PMID 37511325, 2023). "TMEM123 labelling tended to disappear from T cell surface soon after their detachment from cancer cells, as TMEM123-labelled protein was internalized in the cytosol, a process that appeared to be slightly faster in CD8+ than in CD4+ T cells." (PMID 37426665, 2023). "Finally, we evaluated the impact of chronological age on the predictive value of CD4 and CD8 SIP T-cells in cancer patients vaccinated by mRNA COVID-19." (PMID 37334387, 2023). "In contrast, CD8+ and CD4+ T cells in the TME exert antitumor effects by recognizing and clearing dysplastic cancer cells, which are highly related to survival outcomes and immunotherapeutic responses in cancer patients." (PMID 37180139, 2023). "They leverage CD4+ and CD8+ effector T cells across cancer types." (PMID 36845151, 2023). "According to the KEGG analysis, CHST11 may participate in PD‐L1 expression and PD‐1 checkpoint pathway in cancer by regulating genes TICAM2, LAT, TLR2, CD4, STAT3, NFKBIE and CD3D." (PMID 36062845, 2023). "Many reports on CD4+ CTL in chronic viral infections, virus-induced cancers, and virus-independent malignancies established the knowledge that CD4+ T cells not only serve as helper cells but also possess direct cytolytic activities, mainly in an MHC II-restricted way." (PMID 37965314, 2023). "Thus, CD4+ CTL are interesting tools for cure approaches in chronic viral infections and cancer, but their potential to induce immunopathology has to be carefully taken into consideration." (PMID 37965314, 2023). "Additionally, expression levels of immunosuppressive markers on CD4+ and CD8+ T cells were greater in cancer mucosa tissue than in normal mucosa tissue." (PMID 37153541, 2023). "The DCs present antigens to CD4+ and CD8+ T cells in the lymph nodes, and as the DCs act at the interface of the innate and adaptive immune systems, they may be used as targets in cancer immunotherapy." (PMID 36982316, 2023). "Moreover, there were more infiltrating FOXP3+ CD4-Treg cells in GSRC than in M/PDA, and the infiltrating proportion of CD8-Teff cells in cancer tissues was lower than that in para-cancerous tissues, especially in GSRC." (PMID 37225691, 2023). "Furthermore, this observation has immunological implications as TAA-presenting DC engage with and activate CD4+ and CD8+ TAA-specific T cells within the paracortex as we demonstrated in a prior BMDC-based cancer vaccine study." (PMID 37580614, 2023). "In the following four subchapters, we will highlight the most important lncRNAs expressed in T cell subsets (CD8+ T cells, CD4+ T cells, regulatory T cells, γδ T cells and NKT cells), describe their mechanism and summarize their relevance during homeostasis and cancer." (PMID 37346034, 2023).